DMD (dystrophin)
Diseases named in the same sentence as DMD in open-access papers (continued):
Sharing a sentence is not in itself a finding about the gene and the disease.
neuromuscular disease (60 papers, 2005 to 2025). "Background/Objectives: X-linked dystrophinopathies are a group of neuromuscular diseases caused by pathogenic variants in the DMD gene (MIM *300377)." (PMID 39767645, 2024). "DMD is a neuromuscular disease with an incidence of 1:5000 boys, who carry mutations in the DMD gene that disrupt the open-reading frame of the dystrophin protein (Dp) in muscle, heart, and brain." (PMID 36980249, 2023). "The trans gene SYNC was found to interact with dystrobrevin (DMD gene) in order to maintain muscle function (during contraction) in mice as well as being associated with neuromuscular disease." (PMID 36344995, 2022). "In this study, therefore, we examined how two neuromuscular diseases, dystrophin-deficiency and laminin-α2-deficiency, altered the proliferation and composition of different subsets of muscle-derived mononucleate cells." (PMID 15817132, 2005). "Serum microRNA profiling of various neuromuscular diseases also revealed a similar dysregulation of particular microRNAs, and a unique diagnostic signature dependent on the mutation of the specific gene such as dystrophin." (PMID 27547731, 2015). "Preclinical data and a well-established safety profile exist from studies in patients with neuromuscular diseases, including DMD (NCT03039686, NCT02515669)." (PMID 39201450, 2024). "Of the patients with diagnostic variants, 1.6% (8/514) had a variant in genes (DMD and EMD) associated with neuromuscular diseases." (PMID 37795486, 2023). "Ideally, an expert in neuromuscular diseases should order and interpret confirmatory studies; however, due to the greater availability of genetic testing for DMD in Brazil in recent years, in the current days, it is expected that other physicians take this approach." (PMID 36918011, 2023). "Using both antibodies, a reduction of the dystrophin signal is detected in a small cohort of plasma samples from DMD patients when compared to healthy controls, female carriers, and other neuromuscular diseases." (PMID 36982290, 2023). "The growing number of clinical trials in neuromuscular diseases and particularly in DMD and BMD, as well as the need for assessment of response to treatment, require new methodologies with highly-sensitive quantification of dystrophin." (PMID 37047330, 2023). "Duchene muscular dystrophy (DMD) is a progressive neuromuscular disease caused by mutations in the DMD gene, resulting in the absence of dystrophin expression leading to membrane fragility and myofibril necrosis in the muscle cells." (PMID 34804433, 2021). "Subject #18 presented a BMD affected brother while in subjects #19 and #20, in absence of previous family history of neuromuscular disease, elevation of CK levels or a muscle biopsy showing abnormal dystrophin expression prompted DMD molecular studies." (PMID 23092449, 2012).
cancer (58 papers, 2011 to 2026). A tumor composed of atypical neoplastic, often pleomorphic cells that invade other tissues. "DMD expression was significantly associated with survival in nine cancers after Bonferroni correction (α = 0.0015), with high expression linked to either improved or worsened outcomes depending on cancer type." (PMID 40832923, 2026). "Currently, most studies on DMD‐associated cancers have ignored the complex pattern of DMD gene product expression and the multiple isoforms of Dp71; our model is also not yet fully tested to this level of complexity." (PMID 40832923, 2026). "We propose this model as a unified framework to explain the opposing survival associations with DMD expression and to guide experimental exploration of the dual role of DMD in cancer." (PMID 40832923, 2026). "We identified nine cancers where high versus low DMD expression was significantly associated with overall survival and present a model for a context‐dependent dual role of DMD in cancer that reconciles previous conflicting reports." (PMID 40832923, 2026). "We investigated the association between DMD expression and stage in 18 different types of primary cancers with available data for stage, gender, and patient’s age at the initial diagnosis." (PMID 36900171, 2023). "Whilst other DMD transcripts and dystrophin proteins may be relevant to tumourigenesis in some specific contexts, our work supports Dp71ab as a ubiquitously expressed key player in DMD‐associated cancers." (PMID 40832923, 2026). "The third group (blue) includes 34 keywords, such as ‘gene’, ‘duchenne’, ‘dmd’, ‘dystrophin’, ‘protein’, ‘mutation’, ‘carriers’, ‘DNA’, ‘deletion’, ‘locus’, ‘duplications’, ‘phenotype’, ‘complex’, ‘cancer’, ‘deficiency’, ‘molecular basis’, ‘central nervous system’, ‘database’ and ‘association’." (PMID 39669562, 2024). "Cluster 3 (blue) contains 34 keywords, including ‘gene’, ‘duchenne’, ‘dmd’, ‘dystrophin’, ‘protein’, ‘mutation’, ‘carriers’, ‘DNA’, ‘deletion’, ‘locus’, ‘duplications’, ‘phenotype’, ‘complex’, ‘cancer’, ‘deficiency’, ‘molecular basis’, ‘central nervous system’, ‘database’ and ‘association’." (PMID 39669562, 2024). "The loss of the dystrophin function in cancer cells contributes to cell movement or metastasis." (PMID 36652260, 2023). "Although a question of cause or effect remains, it is now clear that a role for DMD in cancer extends beyond just myogenic or musculoskeletal tumours and that the ratio of Dp427 to Dp71 may have particular importance." (PMID 33188621, 2021). "A common basis may underlie the frequent occurrence of CFS/DMD rearrangements in germ cells of DMD patients and similar alterations found in cancer cells." (PMID 33188621, 2021). "Indeed, not only does loss of dystrophin affect synaptic transmission and has recently been found to cause susceptibility to malignant tumors in mice, it also affects activity of Akt, a kinase that directly regulates TSC2." (PMID 24204314, 2013). "Similarly, mutations in DMD have been implicated in the development of various cancers." (PMID 41179682, 2025). "Taken together, these results highlight some inconsistencies when evaluating total DMD expression in cancer, as high DMD expression may be associated with the progression of certain cancers whereas low expression may be associated with the progression of others." (PMID 33188621, 2021). "We also found that the relatively poorly characterised dystrophin isoform, Dp40, was expressed in all nine cancers." (PMID 40832923, 2026). "We focussed our survival analysis on Dp71ab expression given it is the most predominant DMD transcript for the largest number of cancers and has a recognised involvement in tumorigenesis." (PMID 40832923, 2026). "While functional validation now exists for several cancers, more work is required to establish clear mechanisms and validate DMD/Dp71ab as a therapeutic target in physiologically relevant model systems." (PMID 40832923, 2026).
cancer (continued). "The direction of hazard and survival trends across (and sometimes within) cancer types varies when comparing high versus low expression of different DMD gene products." (PMID 40832923, 2026). "Our study examines how DMD, its gene variants, and DAPC gene expression are linked to patient survival outcomes and aims to theorise why survival trends differ by cancer type." (PMID 40832923, 2026). "While our findings provide strong support for a dual role of DMD in cancer, we acknowledge limitations." (PMID 40832923, 2026). "We recently reviewed the literature surrounding the involvement of DMD across all major cancer types, including HNSCC4." (PMID 40155657, 2025). "This work adds to the accumulating evidence for an important role of dystrophin in cancer which warrants further investigation in more complex disease models." (PMID 40155657, 2025). "Consistent with this improvement in a cancer setting, the specific inhibition of BiP using HM03 resulted in significant rescue in muscle function in dystrophin-deficient zebrafish." (PMID 38530354, 2024). "Age of patients was also found to have an impact on DMD gene expression (p < 0.001) as well as the interaction between age and cancer stage (p = 0.003)." (PMID 36900171, 2023). "According to these data, the RAB3C/dystrophin protein has prognostic value in cancer progression, and it can be used as a therapeutic target for improving the survival rates of patients." (PMID 36652260, 2023). "The overall survival of cancer patients with decreased DMD expression in tumors was 27 months lower than that of patients with high DMD expression." (PMID 36900171, 2023). "A GLM analysis was performed to assess the effect of cancer stage on DMD expression while accounting for gender and age differences." (PMID 36900171, 2023). "The differential expression of DMD between pan-cancer and corresponding control tissues was also investigated, revealing that 55% (18 out of 33) of cancer types had abnormal DMD expression." (PMID 34945000, 2021). "We hope to stimulate further study into the potential role of DMD gene products in cancer and the development of novel therapeutics that target DMD." (PMID 33188621, 2021). "This highlights the protective potential of epicatechin against the chemotherapy-induced reduction of dystrophin expression shown by our group, and in cancer-induced cachectic myopathy in which dystrophin is also reduced." (PMID 34298829, 2021). "For example, oncogene products of KRAS and dystrophin (DMD) proteins demonstrated reduced expressions in several cancer types, in spite of the up-regulated status of these oncogenes." (PMID 33287876, 2020). "Amongst potential biomarkers, genes NCKAP1L and DMD are highlighted due to their implications in a considerable portion of lung and bronchus primary carcinomas." (PMID 31766738, 2019). "Among the SNV top-ranked promoters (DMD), DHS elements (LRMP) and enhancers (PAX5, BACH2, BCL2, CXCR4, and BCL7A) are highly cancer-type-specific cases with many BCL or CLL mutations." (PMID 29354286, 2018). "The results showed that six cRMGs including OBSCN, CDKN2A, CSMD3, DMD, DNAH5, and KMT2Cwith MS or NS mutations have significant associations with prognosis in several cancer types." (PMID 30107644, 2018). "According to the mouse insertional mutagenesis experiments, three of these genes (DMD, MYO9A, and COL5A2) have been identified as cancer-causing genes." (PMID 28938601, 2017).
cancer (continued). "Somatic deletions of DMD exons have been identified in cancers with myogenic programs, enhancing their metastatic potential." (PMID 28546788, 2017). "Our results indicated that the DMD gene in CRL-2061 cells is structurally normal, although its transcripts are abnormal, suggesting that post-transcriptional modifications of DMD should be analyzed as a secondary gene alteration in cancers." (PMID 28546788, 2017). "One showed somatic genomic exon deletions in cancers with myogenic programs, whereas the other two showed that dystrophin expression was reduced in gastrointestinal cancers and in other non-myogenic cancers." (PMID 28546788, 2017). "These included homozygous variants calls in genes related to cancer (BRCA1, APC, MEN1), congenital malformation syndromes (TCOF1), metabolic deficiencies (FBP1, HEXA), and neurological diseases (FUS, MLC1, DMD)." (PMID 26547235, 2015). "Another interesting observation is the involvement of DMD gene in our patients (GIST_131, GIST_174, GIST_178 and GIST_188), as it has recently been reported in cancers with myogenic programs." (PMID 26544626, 2015). "Moreover, these two SBS subtypes differed in somatic mutations in several cancer driver genes, including higher mutation frequency of ERBB2, GATA3 and FGFR4, and lower frequency of DMD, INHBA, OGDHL, PLEKHG5 and RYR2 in subtype 3 than in subtype 1 (P < 0.05)." (PMID 40858906, 2025). "To rule out that the observed cancer risk increase was explained by DMD and BMD alone, we performed sensitivity analyses excluding patients with these diagnoses in the NPR." (PMID 39298705, 2024). "Cancer stage was found to have an effect on DMD expression (p = 0.035)." (PMID 36900171, 2023). "Interestingly, in carcinoma cell lines with low DMD expression, the majority of DEGs were downregulated (n = 976 out of 998)." (PMID 36900171, 2023). "Somatic DMD gene mutations and/or defective dystrophin expression has been found in various types of cancer, including non-myogenic tumors in humans." (PMID 35790299, 2022). "Although case reports of cancer in Duchenne patients are rare and confined to round cell tumours to date, a growing and intriguing collection of evidence implicates the DMD gene and/or its protein products in tumourigenesis." (PMID 33188621, 2021). "Recently, increasing evidence has suggested the role of DMD abnormality in cancer development." (PMID 34945000, 2021). "We note that the normal balance of DMD gene products is often disrupted in cancer." (PMID 33188621, 2021). "Interestingly, current research identified a cancer suppressive role of full-length dystrophin in myogenic cancer." (PMID 27449096, 2016). "To validate the model, we examined additional cancers known from the literature to also be significantly associated with DMD expression but that were not identified as significant in our bioinformatic analysis when stringently adjusting for multiple comparisons." (PMID 40832923, 2026). "Furthermore, the role of SMAD3 in DMD shares mechanistic similarities with its function in cancer metastasis, where it regulates cellular proliferation, migration, and invasion—processes similarly detrimental in DMD albeit through different pathological outcomes." (PMID 39415830, 2024). "To determine whether the RAB3C and dystrophin are related to the clinicopathological parameters of cancer patients, we performed the IHC staining of dystrophin and RAB3C on the colorectal tissue arrays to assess whether their expressions can be considered predictors of a poor prognosis in CRC." (PMID 36652260, 2023). "Thus, the DMD gene may play similar roles in cancer and development, two processes showing biological and molecular similarities." (PMID 36900171, 2023).
cancer (continued). "However, increasing evidence implicates DMD in the development of all major cancer types." (PMID 33188621, 2021). "Similarly, higher cancer rates have not been reported in patients who carry mutations in dystrophin or α-sarcoglycan, two other components of the DGC that have been linked to RMS." (PMID 31054580, 2019). "Furthermore, some of the positively selected genes might also be related to cancer, such as DMD, MYO9A, and COL5A2, which have been identified as cancer-causing genes based on mouse insertional mutagenesis experiments." (PMID 28938601, 2017). "We comprehensively explored the prognostic significance of DMD and DAPC gene expression across TCGA cancer types." (PMID 40832923, 2026). "Samples from patients with stage I cancer had significantly higher levels of DMD gene expression compared to those with stage II (LogFC = 0.72, p < 0.001), stage III (LogFC = 0.50, p < 0.001), and stage IV cancer (LogFC = 0.69, p < 0.001)." (PMID 36900171, 2023). "Second, the proposed approach also enables identification and exploration of driver genes; our analyses implicate DMD, RSK4, OFD1, WDR44, and AFF2 as potential cancer drivers." (PMID 35753349, 2022). "Because defective dystrophin expression has been implicated not only in myogenic but also non-myogenic cancers in mice and men, we hypothesized that the canonical full-length dystrophin isoform Dp427m might be a centrosome constituent also in cells other than muscle cells." (PMID 35790299, 2022). "Expression of the target genes (DMD and CXCL12) was also downregulated in precancers and cancer tissues probably due to upregulation of mir31 in these tissues." (PMID 27597234, 2016). "As such, DMD intron retention cannot be ruled out as a potential mechanism for Dp427 inactivation in some cancers." (PMID 33188621, 2021). "This indicates that altered DMD gene products in the brain can disrupt nervous system function regardless of cancer." (PMID 33188621, 2021). "TG003 is known to increase the production of the dystrophin protein without severe cytotoxicity, whereas our compounds show growth inhibition in cancer cells." (PMID 25581376, 2015). "In addition, we found five genes with CNA losses (DMD, ARID1A, RB1, RAD51B and PTEN) that overlapped pan-cancer CNA drivers." (PMID 26429873, 2015). "No studies have yet ascertained whether the DMD gene plays a driving role in cancer or whether findings such as ours are passenger effects." (PMID 40155657, 2025). "Interestingly, a putative role for the DMD gene was also suggested in various non-myogenic cancers, including carcinomas, melanoma, leukemia, lymphoma, and CNS tumors." (PMID 36900171, 2023). "In our proposed DMD-related lncRNA-mRNA pathway networks, PYCARD, RIPK2, and CASP1 were significantly enriched in the NOD-like receptor signaling pathway, whereas MAP2K2, LUM, RPS6, PDCD4, TWIST1, and HIF1A were significantly enriched in proteoglycans in cancers." (PMID 36619896, 2022).